WNT7A (Wnt family member 7A)
Diseases named in the same sentence as WNT7A in open-access papers (continued):
Sharing a sentence is not in itself a finding about the gene and the disease.
ovarian cancer (continued). "In the present study, we report that WNT7A is a direct target of miR-15b in ovarian cancer." (PMID 27195958, 2016). "Recent in vivo mouse studies suggest that WNT7A is an inducer of ovarian cancer growth." (PMID 23762861, 2013). "It was shown that WNT7A regulates tumor growth and progression in ovarian cancer." (PMID 23202957, 2012). "In addition, Wnt7a expression was exclusively high in the malignant ovarian carcinomas and involved in increased migration and invasive capacity in an ovarian cancer cell line OVCAR3, acting as an oncogenic gene." (PMID 23304155, 2012). "However, research results from ovary cancer demonstrated that WNT7A could promote the process of the tumor." (PMID 32174831, 2020). "In addition to PAX8, COPA complemented with pan-cancer analysis prioritized eight other lineage-restricted outliers (CDH6, CLDN16, FGF18, FOLR1, SLC34A2, SOX17, SPON1, WNT7A) displaying largely confined gene expression in ovarian cancer cell lines and tumor specimens." (PMID 31050342, 2019). "However, 8 of the 11 ovarian cancer cell lines showed expression of WNT7A." (PMID 19849863, 2009). "Interestingly, CAFs, which are intimately linked to ovarian cancer progression, are frequently activated by TGF-β or Wnt signaling pathways in HGSC and other tumor types, and this process can be driven by WNT7A, a LowerT gene belonging to our STRATsig signature." (PMID 39568014, 2024). "In the ovarian cancer case study the method revealed the two additional genes characteristic for the cellular quiescence: PI16 and WNT7A." (PMID 29362714, 2017). "We have recently reported that the upregulation of WNT7A (uniquely among 19 WNT ligands) results in accelerated development and progression of ovarian cancer (OvCa), and plays a critical role in tumor progression mediated by the WNT7A/CTNNB1 signaling pathway." (PMID 27195958, 2016). "HOSE cells did not have detectable expression of WNT7A as determined by real time PCR, nor did 3 ovarian cancer cell lines." (PMID 19849863, 2009). "The fact that WNT7A is expressed in CS2 but not in CS1 is also consistent with the hypothesis that CS2 may be a more conducive microenvironment for ovarian cancer growth than CS1." (PMID 23762861, 2013). "The function of WNT7A has not previously been examined in ovarian cancer." (PMID 19849863, 2009).
non-small cell lung carcinoma (16 papers, 2006 to 2025). A group of at least three distinct histological types of lung cancer, including non-small cell squamous cell carcinoma, adenocarcinoma, and large cell carcinoma. "In non-small cell lung cancer cell lines, activation of β-catenin independent signaling, via Wnt7a/Frizzled9 signaling, leads to reversal of cellular transformation, reduced anchorage-independent growth and induction of epithelial differentiation." (PMID 23862015, 2013). "Normally WNT7A maintains epithelial differentiation and inhibits growth of the transformed cell in a subset of human Non-Small Cell Lung Cancer (NSCLC)." (PMID 23202957, 2012). "In support this concept, non-small-cell lung cancer cells transformed with Wnt7a showed inhibition of anchorage independent growth." (PMID 16438732, 2006). "In non-small cell lung cancer, peroxisome proliferator-activated receptor γ (PPARγ), a downstream target of Wnt7A/Fzd9 signaling, inhibits non-small cell lung cancer cell proliferation by up-regulating SPRY4 expression levels through regulating SPRY4 promoter activity." (PMID 38686189, 2024). "WNT7A is a known tumor suppressor gene of non-small cell lung carcinomas (NSCLC) and is frequently inactivated due to CpG-island hypermethylation in such human cancers as lung, pancreatic and oral squamous cell carcinomas (OSCC)." (PMID 23056560, 2012). "Wnt7a stimulates JNK activation and c-Jun phosphorylation in non-small cell lung cancer cells." (PMID 27438150, 2016). "In bladder and oral squamous carcinomas, it promoted cancer cell invasion and migration via a canonical β-catenin-dependent signaling pathway, whereas Wnt7a overexpressed in non-small cell lung cancer enhanced tumor radiosensitivity via a non-canonical Wnt/JNK pathway." (PMID 36096830, 2022). "WNT7A (wingless-type MMTV integration site family, member 7A) is a known tumor suppressor gene of non-small cell lung carcinomas (NSCLC) and is frequently inactivated due to CpG-island hypermethylation in human cancers." (PMID 23056560, 2012). "On the other hand, in non-small cell lung carcinoma (NSCLC) and gastric cancer (GC), WNT7A has been found to act as a tumor suppressor via non-canonical Wnt signaling." (PMID 32174831, 2020).
pancreatic cancer (13 papers, 2012 to 2026). "qRT-PCR analyses revealed that the gene expression of Wnt7A and β-catenin was significantly increased in pancreatic cancer cells overexpressing CAV2 (P < 0.05)." (PMID 35517414, 2022). "The continuous activation of the Wnt pathway and the overexpressions of canonical Wnt ligands (Wnt2, Wnt5a, and Wnt7a’s) are also observed in pancreatic cancer." (PMID 35686109, 2022). "MiR-4723/Wnt7A constitutes an oncogenic signalling axis in pancreatic cancer by targeting and inhibiting Wnt7A through the activation of MiR4723, but its molecular action mechanism remains unexplored." (PMID 35517414, 2022). "On the other hand, the luciferase assays revealed that, after the overexpression of MiR-4723 in both pancreatic cancer cell lines, the luciferase activity of wild-type Wnt7A was reduced." (PMID 35517414, 2022). "We also demonstrated, for the first time, that CAV2 can regulate the MiR-4723/Wnt7A signalling axis in pancreatic cancer cells by inhibiting endocytosis and promoting EMT, thereby accomplishing its pro-cancer effects." (PMID 35517414, 2022). "To investigate the mechanism by which CAV2 promotes pancreatic cancer, we identified Wnt7A as a potential target of CAV2 by using the TCGA database and bioinformatics analyses, whereby CAV2 seems to be the key regulator of Wnt7A." (PMID 35517414, 2022). "Western Blotting results revealed that the protein expression of Wnt7A and β-catenin were significantly increased in pancreatic cancer cells overexpressing CAV2, and their greyscale values were statistically significant (P < 0.05)." (PMID 35517414, 2022). "Here, we are the first to demonstrate that CAV2 exerts a pro-carcinogenic effect on pancreatic cancer through the activation of the Wnt7A/β-catenin signalling pathway." (PMID 35517414, 2022). "Through qRT-PCR and Western blotting, we determined that the upregulation of CAV2 promotes the expression of Wnt7A, β-catenin gene, and proteins in pancreatic cancer cells." (PMID 35517414, 2022). "In summary, we conclude that CAV2 is an oncogenic gene in pancreatic cancer that exerts its oncogenic effect by targeting Wnt7A to activate the Wnt/β-catenin signalling pathway activity." (PMID 35517414, 2022). "To further verify the relationship between MiR-4723 and Wnt7A/β-catenin, we performed qRT-PCR assays and concluded that the Wnt7A expression was downregulated in pancreatic cancer cells after the upregulation of MiR-4723." (PMID 35517414, 2022). "These analyses yielded results showing that the correlation of expression trends between CAV2 and Wnt7A was significantly higher in pancreatic cancer and its paracancer tissues." (PMID 35517414, 2022). "The Wnt7A protein and gene expression was reduced in pancreatic cancer cells overexpressing MiR-4723 and increased in cells overexpressing CAV2." (PMID 35517414, 2022). "Inhibition of WNT7A disrupts Wnt/β-catenin signaling in pancreatic cancer cell lines and suppresses proliferation." (PMID 33648511, 2021). "We show that PG545, by directly interacting with Wnt3a and Wnt7a, inhibits Wnt/β-catenin signaling leading to inhibition of proliferation in pancreatic tumor cell lines." (PMID 25669977, 2015). "Wnt3a is considered a major initiating factor in the Wnt/β-catenin canonical pathway and Wnt7a has been shown to be highly expressed in pancreatic cancer cell lines." (PMID 25669977, 2015). "The Wnt7a gene was also found to be downregulated because of hypermethylation at high frequency in pancreatic carcinoma." (PMID 23304155, 2012). "In accordance with the suppressing effects in NSCLC, Wnt7a was also found to be hypermethylated at high frequency in pancreatic carcinoma." (PMID 23304155, 2012). "In addition, the CAV2 protein expression was reduced in pancreatic cancer cells overexpressing MiR-4723 and increased in cells overexpressing Wnt7A." (PMID 35517414, 2022). "In comparison, the WNT7A gene was hypermethylated in pancreatic carcinomas (71%) and OSCC (78%)." (PMID 23056560, 2012).
pancreatic cancer (continued). "However, in contrast to the studies above, Wnt7a was overexpressed in the cell lines of colorectal carcinoma, pancreatic carcinoma, gastric carcinoma, and breast carcinoma." (PMID 23304155, 2012). "In conclusion, the results above demonstrated that hypoxia induced high expression of WNT7A might promote the cell migration via contributing to the epithelial–mesenchymal transition in pancreatic cancer and WNT7A might be a new biomarker for patients’ survival in PDAC." (PMID 30361522, 2018). "Collectively, these data indicate that WNT7A/7B ligands and WNT receptors FZD1 and FZD6 mediate the paracrine signalling between pancreatic cancer cells and stellate cells in the tumour." (PMID 38678032, 2024). "In pancreatic cancer, direct Wnt pathway activation by upregulation of Wnt family member 2 (WNT2) and Wnt family member 7A (WNT7A) has frequently been observed, resulting in poor clinical outcomes." (PMID 36765639, 2023). "When compared to the control group, the protein and gene expression of PDGFR and EGFR was significantly lower in pancreatic cancer cells overexpressing MiR-4723, while it was significantly higher in cells overexpressing CAV2 or Wnt7A." (PMID 35517414, 2022). "This experiment aimed to explore the effects of CAV2 and MiR-4723 on pancreatic cancer and deeply explore the role and mechanism of CAV2 in MiR-4723/Wnt7A." (PMID 35517414, 2022). "Cancer cell-derived factors, Wnt7a via TGF-β-dependent signaling in breast cancer and galectin-3 via integrin beta 1/ILK/NF-κB signaling in pancreatic cancer, have been reported to be involved in the malignant transformation of fibroblasts and stellate cells." (PMID 34885065, 2021). "MiR-4723 and CAV2 are mutually suppressive in the Wnt7A/β-catenin pathway, and CAV2 can regulate the MiR-4723/Wnt7A pathway by inhibiting endocytosis promoting EMT, which ultimately promotes the proliferation, invasion, and metastasis of pancreatic cancer." (PMID 35517414, 2022). "We found pancreatic cancer tissue demonstrated a significant high WNT7A expression compared with the adjacent non-tumor tissue and the expression of WNT7A positively correlates with poor prognosis and lymph node metastasis." (PMID 30361522, 2018). "In accordance with the observations in tissues, the expression of WNT7A was obviously higher in five pancreatic cancer cell lines than that in nonmalignant hTERT-HPNE cells at both mRNA and protein levels." (PMID 30361522, 2018). "PG545 interacts with Wnt3a and Wnt7a to preventing them from binding to their receptors, LRP5/6 and Frizzled, resulting in significantly decreased β-catenin levels, suppressed tumor growth and metastasis in pancreatic tumors." (PMID 25669977, 2015). "Thereby CAV2 may affect the MiR-4723/Wnt7A pathway through EMT, thus promoting pancreatic cancer." (PMID 35517414, 2022).
endometrial cancer (11 papers, 2012 to 2024). Primary or metastatic malignant neoplasm involving the endometrium (mucous membrane that lines the endometrial cavity). "In conclusion, we have shown that lost or reduced Wnt7a expression is significantly associated with poor progression-free and overall survival in patients with endometrial carcinoma." (PMID 23304155, 2012). "For example, the overexpression of WNT-7A exerts pathogenic effects, and the WNT-7A and WNT-7B expression levels were found to be higher in endometrial carcinoma cell lines than in normal primary endometrial cultures." (PMID 37176048, 2023). "In a large-scale population study of 244 endometrioid endometrial cancer patients, the WNT7A gene was overexpressed in most cases of endometrial cancer." (PMID 34068065, 2021). "Consist with those results, high expression of WNT7A was found in many cancers including endometrial cancer and ovarian cancer." (PMID 30361522, 2018). "In the present study, we also investigated the expression of β-catenin and Wnt7a, which belong to the Wnt pathway, to determine the expression changes in the endometrial cancer cell line of RL95-2." (PMID 28640224, 2017). "In large-scale population study on 244 EEC patients, WNT7A overexpression was found in most cases of endometrial cancer in comparison with normal endometrium and benign endometrial lesion." (PMID 26366420, 2015). "In endometrial cancer cells, Wnt7a interacts with various receptors to stimulate the canonical Wnt pathway and Wnt/JNK pathway." (PMID 25170755, 2014). "A previous study demonstrated that sFRP4 bound to Wnt7a and inhibited canonical Wnt7a signaling in human endometrial cancer cells." (PMID 25170755, 2014). "Further studies on a larger cohort of patients and Wnt7a targeting molecules are warranted to validate the prognostic impact of Wnt7a expression on survival in endometrial cancer." (PMID 23304155, 2012). "In the present study, we examined the status of Wnt7a expression in normal, hyperplastic, and malignant endometrium and analyzed its possible roles in the clinical outcome of patients with endometrial cancer." (PMID 23304155, 2012). "In endometrial carcinoma Ishikawa cell line, estrogens decreased Wnt7a expression through its receptor ER." (PMID 23304155, 2012). "The aim of this study is to investigate the expression and prognostic significance of Wnt7a in endometrial carcinoma." (PMID 23304155, 2012). "Wnt7a expression was lower in endometrial carcinomas (26/70, 37.1%) compared with that in normal endometrium (31/35, 88.6%) and hyperplastic endometrium (26/33, 78.8%) (P < 0.001 and P < 0.001, resp)." (PMID 23304155, 2012). "In, accordance with endometrial carcinoma, an inverse correlation was apparent between Wnt7a and ERα expression in human uterine leiomyoma." (PMID 23304155, 2012). "In addition to WNT7A, the expression of WNT10A and WNT10B ligands has been associated with estrogen-related carcinogenesis of endometrial cancer." (PMID 34068065, 2021). "In one clinical study of endometrial carcinoma, the expression of WNT7A gene was absent or reduced and was negatively linked with FIGO stage, grade, lymph node metastasis, depth of myometrial invasion, and peritoneal cytology in approximately 60% of patients." (PMID 34068065, 2021). "Therefore, it is warranted to investigate the major Fzd receptor expression interacting with Wnt7a on the endometrial carcinoma cell surface." (PMID 23304155, 2012). "We could demonstrate for the first time that lost or reduced Wnt7a expression was correlated with disease progression and Wnt7a might be a useful prognostic factor in endometrial carcinoma." (PMID 23304155, 2012). "Furthermore, we analyzed the association of Wnt7a expression with clinicopathological characteristics and outcome of patients with endometrial carcinomas and evaluated the correlation between Wnt7a expression and the hormone receptor status." (PMID 23304155, 2012).
endometrial cancer (continued). "The estrogen receptor (ER) antagonist could reverse the reduction of Wnt7a by estrogens in endometrial carcinoma cell line, thus indicating that the downregulation of Wnt7a was partly mediated by the ER." (PMID 23304155, 2012). "Wnt7a has also been detected in endometrial carcinoma cell lines and endometrial tumors." (PMID 23304155, 2012). "Furthermore, the observed negative correlation between Wnt7a and ER status but positive correlation between Wnt7a and PR status in endometrial carcinoma indicated a link between Wnt7a and ovarian hormones." (PMID 23304155, 2012). "Importantly, a recent study suggested WNT7a to decrease growth of endometrial cancer cell lines." (PMID 35885035, 2022). "However, less is understood about the role of Wnt7a in human endometrial carcinoma." (PMID 23304155, 2012). "Our data suggest downregulation of WNT7a by DSCAM-AS1, which is overexpressed in endometrial cancer, so this interaction might contribute to endometrial carcinogenesis." (PMID 35885035, 2022). "It is important to note, however, that the lack of expression of WNT7A positively correlated with overall survival and disease-free survival in endometrial cancer patients, suggesting that overexpression of WNT7A plays a pathogenic role." (PMID 34068065, 2021). "Moreover, WNT7A and WNT7B genes expression was increased in endometrial carcinoma cell lines and normal endometrial tissues as compared with primary cultures of human endometrial cells." (PMID 26366420, 2015). "SFRP4 also suppresses, depending on the receptor, Wnt-7a-induced proliferation via canonical and non-canonical pathways in endometrial cancer cell lines." (PMID 22363760, 2012). "Wnt7a expression was inversely correlated with FIGO stage (P = 0.001), grade (P = 0.001), lymph node metastasis (P = 0.002), depth of myometrial invasion (P = 0.006), LVS involvement (P = 0.001), and peritoneal cytology (P = 0.013) of endometrial carcinomas." (PMID 23304155, 2012). "Absent or reduced Wnt7a expression was detected in the majority of endometrial carcinoma, but only in 21.2% of endometrial hyperplasia and 11.4% in normal endometrium." (PMID 23304155, 2012). "Furthermore, in patients with endometrial cancer, a lack of expression of WNT-7A was positively correlated with overall survival." (PMID 37176048, 2023). "However, negative expression of WNT7A gene correlated positively with overall survival and disease-free survival of endometrial cancer." (PMID 26366420, 2015). "In 63% patients of one series of endometrial carcinoma, WNT7A gene expression was absent or reduced and negatively correlated with FIGO stage, grade, lymph node metastasis, depth of myometrial invasion, lymph vascular space involvement, and peritoneal cytology." (PMID 26366420, 2015). "However, a wide range of Wnt7a mRNA expression in endometrial carcinoma was not consistent with our present study." (PMID 23304155, 2012). "The expression of WNT7A and WNT7B genes is high in endometrial carcinoma cell lines but not in normal primary endometrial cultures." (PMID 34068065, 2021). "However, NOMAC did not significantly inhibit the growth of the type II endometrial cancer cell line of KLE, and did not significantly upregulate the expression of SUFU and Wnt7a in the KLE cells." (PMID 28640224, 2017). "In summary, at the tested concentrations, the mechanism of action of NOMAC may be involved in the regulation of the activity of SUFU and Wnt7a in type I endometrial cancer cell line RL95-2 and RL95-2 xenograft tumor tissues, but not in type II endometrial cancer cell line KLE." (PMID 28640224, 2017). "We demonstrated that Wnt7a negative expression was inversely correlated with FIGO stage, grade, lymph node metastasis, depth of myometrial invasion, LVS involvement, and peritoneal cytology, indicating that Wnt7a functioned as a tumor-suppressing factor in endometrial carcinoma." (PMID 23304155, 2012).